BAX (BCL2 associated X, apoptosis regulator)
Diseases named in the same sentence as BAX in open-access papers (continued):
Sharing a sentence is not in itself a finding about the gene and the disease.
colon carcinoma (continued). "Most cell lines exhibited higher, cumulative expression levels of BAK and BAX when compared to cumulative expression levels of anti-apoptotic BCL2 proteins, as previously observed in colon cancer cells." (PMID 29352235, 2018). "This pathway is already reported in other cancer cells (prostate cancer and colon carcinoma) to induce apoptosis to overcome the absence of BAX." (PMID 41282624, 2025). "When assessing colon cancer cells under similar conditions, elevated BAX levels were noted in both the RJ- and RJ + AVE treatment groups, while no significant variation was observed in the AVE treatment group." (PMID 39838121, 2025). "This hypothesis was tested by screening the gene expression profile in wild type DLD-1 colon cancer cells (DLD-1 WT cells) and the isogenic line ablated with both BAX and BAK (DLD-1 BAX–BAK DKO cells) using the human cancer drug resistance PCR array." (PMID 31551763, 2019). "Subsequently, the effect of BAX and BAK double knockout in the mitochondrial respiration rates in DLD-1 colon cancer cells was analyzed by measuring the OCR of DLD-1 cellular models with the use of different inhibitors or stimulators of the mitochondrial respiratory pathway." (PMID 31551763, 2019). "PCR array analysis for the transcriptional profiling of genes related to human cancer drug resistance validated the altered level of 12 genes (3 upregulated and 9 downregulated) in DLD-1 colon cancer cells lack of BAX and BAK expression." (PMID 31551763, 2019). "However, no WWOX-induced changes were observed in the transcription of apoptosis-related genes (BAX, BCL2, BIRC5), whose expression was observed to correlate with WWOX in colon tumour specimens and other cancer tissues." (PMID 24938873, 2014). "Moreover, in colon cancer, the pathway of AKT/Bcl-2/BAX could promote the metastasis of colon cancer cells." (PMID 39074253, 2024). "In the cell culture, LS174t colon cancer cells were treated with OB extract, CuNPs, and OB-coated CuNPs with and without different radiation levels in order to assess cell viability, through the MTT assay, and the pro-apoptotic BAX and anti-apoptotic BCL2 expressions, through qPCR assay." (PMID 39044767, 2024). "DDMP-induced apoptosis in colon cancer cells (SW620 and HCT116) via the modulation of the activity of NF-KB, where it suppressed the antiapoptotic genes (BCL2), whereas it induced the expression of the apoptotic genes (BAX, cleaved caspase-3, and cleaved PARP)." (PMID 35956468, 2022). "While it has initiated DNA fragmentation via activation of BAX and inhibition of BCL2 and BCL-XL (encoded by the BCL2L1 gene) in laryngeal carcinoma Hep-2 cells and colon carcinoma HL-60 cells, a decrease in BCL2 without alteration in BAX was reported in another study using U937 leukemic cells." (PMID 31873082, 2019). "Recently, Panaretakis found that anthracycline drugs mitoxantrone and oxaliplatin can stimulate ER stress in colon cancer cell line CT26, activate the phosphorylation kinase of ER elF2α, resulting in the phosphorylation of elF2α and structural changes of caspase-8, apoptosis regulators BAX and Bak." (PMID 28938593, 2017). "Unlike the other colon cancer cell lines studied, KM12 cells do not express detectable levels of pro-apoptotic BAX." (PMID 24185264, 2013).
colon carcinoma (continued). "Unlike the other colon tumor cell lines in that study, including HCT116 cells, KM12 cells do not express the pro-apoptotic BCL2 family member BAX." (PMID 24185264, 2013). "Despite the block in apoptosis and greatly reduced total cell death in the absence of BAX, we observed that the overall in vitro sensitivity determined by SRB or MTT assays was no different between BAX+/− and BAX−/− HCT116 human colon cancer cells." (PMID 24185264, 2013).
melanoma (66 papers, 2011 to 2025). A malignant, usually aggressive tumor composed of atypical, neoplastic melanocytes. "We then engineered the melanoma cell lines with loss-of-function alterations (BAX or FAS knockdown or over-expression of a dominant-negative DFFA [DFFA-cleavage-resistant [CR]]50) that mimic deletions of pro-apoptotic genes, testing one gene at a time." (PMID 41175874, 2025). "Literature evidence showed that in some melanoma patients, raised levels of BAX were associated with the initiation and progression of malignant melanoma." (PMID 40321146, 2025). "A more recent study showed that low SMAC H-score (and BAK and BAX) was associated with longer progression-free survival in chemotherapy-treated patients with melanoma, and this was further verified with analysis of The Cancer Genome Atlas (TCGA) data." (PMID 39886119, 2024). "Here, we report the ability of PEL and EPI to cause apoptosis in melanoma cells through the contemporaneous increase in pro-apoptotic BAX mRNA expression and decrease in the anti-apoptotic BCL-2, BIRC-5, and MCL1 mRNA expression." (PMID 35877720, 2022). "ALOC-EO induced apoptosis in treated melanoma cells with the upregulation of the intrinsic apoptotic pathway-associated BAX protein." (PMID 34360915, 2021). "Quantitative real-time polymerase chain reaction (RT-qPCR) analysis revealed that the triterpene-GNP conjugate treated A375 melanoma cells had a fold change increase in Bcl-2-associated X protein (BAX) expression and a fold change decrease in B-cell lymphoma 2 (Bcl-2) expression." (PMID 36615613, 2023). "This downregulation of ERK led to reduced PKM2 activation, decreased expression of the anti-apoptotic protein Bcl-2, and increased expression of the pro-apoptotic protein BAX, collectively promoting apoptosis in melanoma cells." (PMID 41463545, 2025). "Knockdown of individual proapoptotic genes (BAX or FAS) partially rescued melanoma cell lines from T cell-induced apoptosis." (PMID 41175874, 2025). "Our data showed that FXT induced an increase in the expression of BAX, Bad, and caspase-9 in melanoma cells, which are key events in the process of cell apoptosis." (PMID 38911391, 2024). "In melanoma cells, MiR-1246 inhibited BAX but stimulated Bcl2, thus inhibiting apoptosis and hepatocyte nuclear factor 3-β/FOXA2 which is involved in embryonic development and activates liver genes." (PMID 38899393, 2024). "The outcomes obtained from this study suggest that PHEC-66 triggers apoptosis in these melanoma cell lines by increasing the expression of pro-apoptotic markers (BAX mRNA) while concurrently reducing the expression of anti-apoptotic markers (Bcl-2 mRNA)." (PMID 38334660, 2024). "BCL2 proteins are those crucial modulators which enclose some pro- and anti-apoptotic factors like BCL2 and BAX and participate in the survival and apoptosis of melanoma." (PMID 39726752, 2024). "In our recent work, we showed that bezotriazole esters of BA, OA and UA, respectively, did reduce the expression of the anti-apoptotic Bcl-2 gene and induced an increase in the fold gene expression of the pro-apoptotic BAX in A375 melanoma cells." (PMID 36615613, 2023). "Pterostilbene induced apoptosis in amelanotic C32 melanoma cells, and this effect was mediated by an increase in the expression of the BAX, CASP9, and CASP9 genes; induction of caspase 3 activity; and DNA degradation." (PMID 36674631, 2023). "It was proposed that upregulation of these MAPK kinases promotes apoptosis in melanoma cells, which was supported by the expression of BAX, BCL-2, and cleaved PARP." (PMID 36829966, 2023).
melanoma (continued). "While these expression patterns are counter-intuitive to cisplatin resistance, similar findings have recently been reported in melanoma, where reduced expression of BAK, BAX and SMAC was associated with increased progression-free survival." (PMID 37898609, 2023). "Quantitative real-time PCR was used to determine gene expression variations of anti-apoptotic Bcl-2 and pro-apoptotic BAX to further establish the pro-apoptotic effects of the three triterpene-gold nanoformulations on A375 melanoma cells." (PMID 36615613, 2023). "Our results also confirmed that dinaciclib‐induced apoptosis seems to depend more on BAK than on BAX, as previously reported for melanoma cells." (PMID 37704591, 2023). "We report here a significantly increased expression of BAX in melanoma patients, supporting it as a possible autoimmunity-related target in melanoma." (PMID 35205739, 2022). "In summary, our results suggest that BAX protein levels can be used to personalize the model, simulate caspase activation, and predict drug-responses for DNA-damaging drugs in melanoma cells." (PMID 33558564, 2021). "Obviously, CBP, Ku70, NOX2, and CBP, Ku70, and BAX are organized into lines of the regulatory network in balancing the oxidative stress for melanoma cells to proliferate." (PMID 33637687, 2021). "provides a possible explanation for this, showing in melanoma cells how dinaciclib is able to induce apoptosis also in a BAX-independent manner via BAK47." (PMID 33686114, 2021). "In melanoma, the ratio of BAX, a pro-apoptotic protein, and Bcl-2, an anti-apoptotic protein, is considered to be important in relation to the susceptibility of melanoma to apoptosis; thus, these proteins are considered as a therapeutic target." (PMID 32722030, 2020). "Next, we took advantage of the live-cell Incucyte Imager system to evaluate the induction of either apoptosis or CICD in BAX-expressing melanoma cells." (PMID 29973136, 2018). "We also observed elevated levels of BAK and BAX expression in melanomas compared to primary melanocytes." (PMID 29348439, 2018). "The results revealed a reduction in BCL-2 protein levels in both melanoma cell lines in parallel with increasing amounts of BAX." (PMID 27399772, 2016). "Additionally, piperine, a natural compound of black peppers, inhibits human melanoma cell growth and induces apoptosis via Caspase/BAX signaling proteins, while suppresses antiapoptotic expression and phosphor-ERK1/2 proteins." (PMID 36923503, 2023). "Similar to its effects on regular melanoma cells, lj-1-59 treatment causes cell cycle arrest at the G2/M phase and apoptosis, including upregulating the expression of cleaved PARP and BAX and decreasing BCL2 expression." (PMID 32021565, 2020). "However, combined exposure of cells to both drugs led to significant changes in BAX mRNA levels in both studied melanoma cells, which may suggest stimulation of the apoptotic pathway." (PMID 41373567, 2025). "CD133 overexpression in BAKR cells also correlates with the dramatic upregulation of basal levels of anti-apoptotic BCL-2 and down-regulation of the pro-apoptotic BAX protein which may tilt the balance towards increased cell survival upon treatment with targeted melanoma therapeutics." (PMID 35216449, 2022). "Finally, we measured BAX and cleaved caspase-3 protein expression levels in CC and melanoma." (PMID 33918641, 2021).
melanoma (continued). "Hence, melanoma cell killing via BH3-mimetic combinations involves both BAX and BAK." (PMID 31019203, 2019). "Previously published studies also described the upregulation of BAX and the downregulation of BCL-2 expression levels in G361 and SK-MEL-2 melanoma cells treated with 0.5 μM binimetinib." (PMID 41373567, 2025). "FXT promotes the apoptosis process in melanoma cells by influencing the expression of key proteins such as γ-H2AX, Akt, BAX, Bad, and caspase-9." (PMID 38911391, 2024). "RT-qPCR analysis showed a fold change increase in the expression of BAX and a decrease in the expression of Bcl-2, which occurred in the triterpene-GNP conjugate-treated A375 melanoma cells." (PMID 36615613, 2023). "We first generated BAX and BAK (BAX-/-BAK1-/-) knockout and wild-type controls in BRAF(V600E) mutant A375 melanoma cells with CRISPR/Cas9 technology." (PMID 36918588, 2023). "BAX expression increased by almost 50% in DPG-treated cells, indicating that melanoma is sensitive to DPG treatment." (PMID 35806253, 2022). "The same trend was observed in melanoma cells treated with EPI, which significantly increased the mRNA expression of BAX and decreased the mRNA expression of BCL2, BIRC5, and MCL-1." (PMID 35877720, 2022). "Since malignant melanoma is characterized by a poor prognosis and resistance to agents inducing apoptosis, the ability of EcTI to reduce BCL-2 and increase BAX confers on these protein-relevant characteristics to sensitize cancer cells to death." (PMID 35566311, 2022). "Our results, therefore, supported the idea that CBP, Ku70, BAX, and NOX2 have formed a transcriptional network in the prevention of cell death of necrosis, paraptosis, and apoptosis in human melanoma." (PMID 33637687, 2021). "The expression of apoptotic genes including BAX, BCL2, and CASP3 was evaluated in B16-F10 melanoma cancer and L929 cells by real-time PCR assay." (PMID 34825002, 2021). "Using similar approaches, and extending to PLX4032 ± BAM15, the melanoma cell lines showed similar phenotypes and requirements for BAK/BAX and caspases to undergo cell death." (PMID 29348439, 2018). "The results showed that VB1 induced cleavage of PARP and upregulated BAX expression, whereas BCL2 expression was downregulated after VB1 treatment in different melanoma cell lines." (PMID 30400954, 2018). "In particular, in melanoma cells, we demonstrate that PG disrupts the interaction between MCL-1 and BAK, allowing the formation of BAK/BAX complex and the subsequent cytochrome c release to the cytosol, which mediates the mitochondrial apoptosis activation." (PMID 23460874, 2013). "BCL10 (3.84-fold), TRADD (2.71-fold), CYCS (2.51-fold), DIABLO (2.43-fold), BAD (2.36-fold), BID (2.17-fold), TNFSF8 (2.13-fold), TNFSF10 (2.11-fold), BAX (2.03-fold), and FAS (2.01-fold) were also proapoptotic genes highly upregulated in response to UA treatment in A-375 melanoma cells." (PMID 39473730, 2024). "EBI3 was evidently highly-expressed in melanoma, and silencing of EBI3 could visibly suppress the survival and migration/invasion of melanoma cells, concurrent with the increased levels of BAX and CDH1 and the decreased expressions of BCL2 and CDH2." (PMID 39726752, 2024). "Our current study has hinted that EBI3 silencing could suppress the proliferation, migration and invasion of melanoma cells, concurrent with the diminished expression of CDH2 and BCL2 yet the upregulated expression of CDH1 and BAX." (PMID 39726752, 2024).
melanoma (continued). "It was found that in resistant melanoma cell lines, the expression of the proapoptotic proteins BAX and MTCH2 were negatively or not correlated to cPARP levels." (PMID 39596009, 2024). "Expression levels of NOD2, BAX, IL-18 and ADRB2 were found to be significantly different in melanoma vs. controls and discriminate melanoma from controls in an extremely effective way, either as single molecules (AUC > 0.93 in all cases) or as a profile, according to the PCA analysis." (PMID 35205739, 2022). "Our main aim was to test whether a mathematical model of the apoptotic switch as regulated by BAX and SMAC could predict the sensitivity of cancer cells, particularly melanoma cells, to DNA damaging drugs." (PMID 33558564, 2021). "In addition to several ECM proteins that were found to be downregulated we also observed upregulation of several pro-apoptotic genes such as BAX, CDKN1A, GADD45A, GADD45B, etc. in TP-472–treated melanoma cells." (PMID 34771678, 2021). "Moreover, this compound induced PARP cleavage and increased BAX expression, whereas BCL2 expression was downregulated after lj-1-59 treatment in different melanoma cell lines." (PMID 32021565, 2020). "As the BAK/BAX-dependent mitochondrial pathway of apoptosis is responsible for BAM15-mediated cell death when oncogenic signaling is inhibited, we determined the expression of BAK and BAX in human melanoma and their relationship to overall survival." (PMID 29348439, 2018). "In addition, GCNT2/I-branched glycan expressing melanoma cells displayed higher levels of proapoptotic genes, BID and BAX, and had lower expression of prosurvival genes, BCL-2 and BCL-XL." (PMID 30135430, 2018). "While ABT737 alone was not sufficient to induce apoptosis in melanoma cells, which abundantly express BAX and BAK, combining ABT737 with MAPK inhibition and BAM15 resulted in massive apoptosis within a few hours." (PMID 29348439, 2018). "As the BAX/BCL-2 ratio seems to be the determinant for setting a threshold for cells undergoing apoptosis, we studied the effect of Lebein on BCL-2 and BAX protein expression to understand its therapeutic potential in melanoma." (PMID 27399772, 2016). "Moreover, by using a BAX and BAK DKO MM cell line we have demonstrated that dinaciclib‐induced death occurs through the intrinsic apoptotic pathway, according to previous studies in mouse embryonic fibroblasts and melanoma cells." (PMID 37704591, 2023). "Concordantly with the gene modulation results, a significant reduction in miR-214-3p, targeting BAX, and a significant up-regulation of miR-16-5p, targeting BCL2 and BIRC5, and of miR-193a-3p, targeting MCL-1, were observed in PEL and EPI -treated melanoma cells." (PMID 35877720, 2022). "Here, we wanted to understand how BAX and SMAC control the emergent properties of the bistable switch and test whether a mathematical model of this switch could predict the sensitivity of melanoma cell lines to DNA damaging drugs." (PMID 33558564, 2021). "Therefore, our results adding up together indicated that CBP, Ku70, NOX2, and BAX have been made up of a transcriptional network in preventing cell death, such as paraptosis and necrosis via NOX2–ROS, and apoptosis via Ku70–BAX–caspases in human melanoma." (PMID 33637687, 2021).